DRAP1 (DR1 associated protein 1)
Description:
The association of the DR1/DRAP1 heterodimer with TBP results in a functional repression of both activated and basal transcription of class II genes. This interaction precludes the formation of a transcription-competent complex by inhibiting the association of TFIIA and/or TFIIB with TBP. Can bind to DNA on its own.
Synonyms: NC2-alpha
Tractability: PROTAC: ubiquitination databases record sites on it; its protein half-life has been measured.
Gene: Protein-coding gene on chromosome 11 (65,919,274 to 65,921,563, forward strand). Ensembl gene ENSG00000175550.
Subcellular location: Nucleus
Subcellular location (Human Protein Atlas): Cytosol
Pathways (Reactome):
Developmental Biology: Signaling by NODAL
Signal Transduction: Signaling by Activin
Gene Ontology:
Molecular function: DNA binding; identical protein binding; protein binding; RNA polymerase II general transcription initiation factor activity; RNA polymerase II general transcription initiation factor binding; TBP-class protein binding; core promoter sequence-specific DNA binding; protein heterodimerization activity; transcription corepressor activity
Biological process: negative regulation of transcription by RNA polymerase II; negative regulation of RNA polymerase II transcription preinitiation complex assembly; transcription by RNA polymerase II
Cellular component: negative cofactor 2 complex; RNA polymerase II transcription regulator complex; nucleus
Genetic constraint (gnomAD): Loss-of-function variants: 10 observed, 22.99 expected, observed/expected ratio (o/e) 0.43, 90% interval 0.27 to 0.74. The upper end of that interval is the gene's LOEUF score, 0.74, which puts it in group 3 of 6, group 1 being the genes least tolerant of losing a copy. Missense variants: 261 observed, 268.26 expected, observed/expected ratio (o/e) 0.97, 90% interval 0.88 to 1.08. Synonymous variants: 120 observed, 109.25 expected, observed/expected ratio (o/e) 1.1, 90% interval 0.95 to 1.28.
Homologues: Orthologues: chimpanzee DRAP1 (100% identical), macaque DRAP1 (99% identical), dog DRAP1 (94% identical), rat Drap1 (94% identical), mouse Drap1 (93% identical), guinea pig DRAP1 (93% identical), pig DRAP1 (93% identical), zebrafish drap1 (73% identical), tropical clawed frog drap1 (70% identical), Drosophila melanogaster NC2alpha (45% identical), Caenorhabditis elegans drap-1 (30% identical). Paralogues in human: NFYC (23% identical), POLE4 (13% identical).
Diseases named in the same sentence as DRAP1 in open-access papers:
DRAP1 is named in the same sentence as 7 diseases in open-access papers, as found by Europe PMC text mining. Sharing a sentence is not in itself a finding about the gene and the disease. The quoted sentences say what the papers report.
atherosclerosis (1 paper, 2025). A disease characterized by the build-up of fatty material and calcium deposition in the arterial wall resulting in partial or complete occlusion of the arterial lumen. "A WGCNA approach was implemented to identify biologically meaningful gene modules highly correlated with the four key atherosclerosis‐associated RGN driver genes (i.e., AIP, DRAP1, POLR2I, and PQBP1)." (PMID 40112173, 2025).
depression (1 paper, 2025). "Through comprehensive molecular regulatory network analysis, transcription factors such as ATF1, IRF1, HBP1, DRAP1, TGIF2, and TFDP1 were identified as potential regulatory factors in depression, warranting further exploration." (PMID 40370590, 2025).
leukemia (1 paper, 2022). A malignant (clonal) hematologic disorder, involving hematopoietic stem cells and characterized by the presence of primitive or atypical myeloid or lymphoid cells in the bone marrow and the blood. "There were many leukemia-related genes in the up-regulated genes of K1 group, such as UBB (P=1.56e-50), MIF (P=2.76e-50), DRAP1 (P=1.72e-49), RPS25 (P=1.9e-49), EIF3K (P=4.77e-49), SSNA1 (P=1.27e-48), GPX4 (P=3.01e-48), PHB2 (P=7.13e-48), NME2 (P=2.44e-47) or CFL1 (P=4.07e-47)." (PMID 36408189, 2022).
infection (1 paper, 2023). The state of being infected such as from the introduction of a foreign agent such as serum, vaccine, antigenic substance or organism. "Since RPL35 and DRAP1 interact with MCE1 exclusively during HIV-1 (SERINC5+) infection, we evaluated whether the expression levels of these host genes affected the viral RNA capping and found that overexpression of the host genes reduced the viral RNA capping even for HIV-1 (SERINC5−)." (PMID 36976020, 2023). "Infection from HIV-1 (SERINC5+) in macrophages upregulated RPL35 by ~5-fold and DRAP1 by ~3-fold at the RNA level, which was, importantly, reversed when the viruses were produced in the presence of viral accessary protein Nef." (PMID 36976020, 2023). "We have also shown that Tat binding to MCE1 is lost only in the case when the infection is initiated with SERINC5 incorporated virus and upon upregulation of RPL35 and DRAP1." (PMID 36976020, 2023). "Infection from HIV-1 (SERINC5+) upregulates RPL35 and DRAP1 in macrophages." (PMID 36976020, 2023).
DRAP1 also shares sentences with these, for which no sentence is quoted: cancer (1 paper); myeloid malignancies (1); papillary renal cell carcinoma (1).